RNU6-889P (RNA, U6 small nuclear 889, pseudogene)
Gene: Small nuclear RNA gene on chromosome 10 (2,098,167 to 2,098,269, forward strand). Ensembl gene ENSG00000252998.
Homologues: Orthologues: chimpanzee U6 (100% identical), macaque U6 (85% identical), dog U6 (60% identical), rat LOC120096368 (60% identical), mouse Gm55001 (51% identical). Paralogues in human: RNU6-378P (69% identical), RNU6-937P (69% identical), RNU6-98P (69% identical), RNU6-1037P (68% identical), RNU6-1097P (68% identical), RNU6-10P (68% identical), RNU6-144P (68% identical), RNU6-33P (68% identical), RNU6-40P (68% identical), RNU6-42P (68% identical), RNU6-46P (68% identical), RNU6-682P (68% identical), and 1285 more.